TLR3 (toll like receptor 3)
Diseases named in the same sentence as TLR3 in open-access papers (continued):
Sharing a sentence is not in itself a finding about the gene and the disease.
infection (continued). "By days 5 and 7 of infection, there was a marked difference in gene expression with heightened expression of Mx1, Tlr3, Ifnα2, Ifnαr1, Ifnβ1, and Il-15 detected in aged lung in response to H1N1." (PMID 34829979, 2021). "Other study using a transgenic mouse deficient for endosomal nucleic acid sensing TLRs (TLR3, TLR7 and TLR9) showed increased parasitism and bigger lesion after 6 weeks post infection." (PMID 34745100, 2021). "Previously, Gowen and coworkers reported that during infection by Punta Toro Virus, another phlebovirus, host TLR3-mediated immunopathology controls mouse morbidity and mortality." (PMID 34310619, 2021). "In response to H1N1 or H3N2, there was increased expression of Il-15, Tlr3, and Stat1 detected in young lung at day 7 of infection." (PMID 34829979, 2021). "Along the same lines, it has been reported that TLR3 activation upon infection of hepatocytes with hepatitis C virus (HCV) only moderately induced ISGs but profoundly induced the production of chemokines and inflammatory cytokines." (PMID 33658344, 2021). "Serum levels of IL-17a at day 2 post-infection and IL-6, and IL-10 at day 3 post-infection are increased in TLR3+/- compared to CB4-infected wt mice." (PMID 34804036, 2021). "The importance of TLR3 expression levels in the progression of infection was also demonstrated through an analysis of peripheral blood." (PMID 34207750, 2021). "After the infection of airway epithelial cells, the influenza virus can be recognized by TLR3 and result in the activation of NF-κB and IRF3." (PMID 34497658, 2021). "ii) TLR3, a receptor for viral dsRNA, displayed a strong reduction in influenza virus and icMERS infection, while TICAM1, TRAF1, TRAF2, TRAF3 and TRAF6, adaptors responsible for TLR3, changed in an opposite direction with TLR3." (PMID 34248940, 2021). "Other than their latent role until the presence of infection, it is noteworthy to investigate the potential functions of TLR3 and TLR4 during development in the future." (PMID 34395439, 2021). "It is worth mentioning that in vitro infection of preadipocytes at much lower MOI (0.01) also led to increased Tlr3, RigI, Mda5, Mx,1 and Vip transcript levels." (PMID 32409640, 2020). "TLR9 and FoxP3 were up-regulated in dog skin at the early stages of infection and in lymph nodes and significant downregulation of TLR3, TLR4, TLR9, IL-17, IL-22, and FoxP3 transcription was found associated with disease progression." (PMID 33352885, 2020). "Upregulation of TLR3 in epithelial lung cells was shown after infection with different strains of MTB." (PMID 32033104, 2020). "High expression levels of IL29 and low IFNB1 expression upon RIG-I and TLR3 activation in our cell line correlates with in vivo findings where HCV-infection of chimpanzees primarily induced the expression of type III IFNs." (PMID 32481600, 2020). "Similar to the results for DTMUV-infected ducklings, MDA5, and TLR3 expression were significantly increased in the early post-infection period compared with other PRRs." (PMID 31947624, 2020). "Eight-week-old toll-like receptor 3 (Tlr3)-deficient female NOD mice showed reductions in the insulitis score and the incidence of T1D upon CVB4 infection." (PMID 32727064, 2020). "In contrast, TLR3, upon upregulation, is located in the endosome, where it is important at later times during infection." (PMID 32481600, 2020). "Collectively, the predominant induction of type III IFNs through activating the TLR3/IRF1 pathway is a common characteristic of IECs upon the infections with enteroviruses." (PMID 33203755, 2020). "It is known that necroptosis can be initiated by activation of TLR3 or TLR4 as well as pathogen infection in addition to activation of death receptors." (PMID 33364238, 2020).
infection (continued). "Consistent with our gene expression data, stimulation of TLR response with TLR3 and TLR7 agonists, showed almost complete suppression of infection for TLR3 stimulation and partial suppression of infection for TLR7 stimulation in one of the fcMSC donors." (PMID 32941515, 2020). "On the other hand, DHF patients who presented a secondary infection had a lower probability of being TLR3-rs3775291-T/T and TLR3-rs6552950-A/G genotypes compared to DF patients." (PMID 33138336, 2020). "In contrast, transcriptomic data from Shaoxin mallard ducks infected with a HPAI H5N1 show increased TLR3 expression in the lungs, peaking on day 2 of infection." (PMID 32477965, 2020). "In comparison, the expression of the endosomal dsRNA sensor, TLR3 upon SAV-2 infection with MOI-10 only showed significantly higher copy numbers at early stages of infection (6–12 h) (p < 0.001)." (PMID 32922394, 2020). "Infection of the human cell line A549 (alveolar epithelial cell line) with IAV resulted in an upregulation of TLR3." (PMID 32477965, 2020). "IFN production in these cells was triggered by the activation of extracellular as well as intracellular pathogen sensing receptors, such as TLR3 and MyD88, as a result of infection, thus leading to a strong anti-viral defense early during CHIKV infection." (PMID 32411133, 2020). "Another study has demonstrated a TLR3-depdendent IP10/CXCL10 response to infection with Xenotropic murine leukemia virus-related virus (XMRV) in two cell lines." (PMID 33202596, 2020). "The results above clearly demonstrated that a TLR3-mediated signaling pathway was essential for defending against DTMUV infection." (PMID 32641107, 2020). "TLR3 is an important PRR that recognizes viral PAMPs early during infection because it is localized to early endosomes, which are hijacked by viruses for cellular entry." (PMID 31156620, 2019). "Nonetheless, PKR is important for the production of IFN-I, IL6, CCL2, and CXCL10 in primary SJL astrocyte cultures, whereas TLR3 plays only a minor role in the responses to a TMEV-BeAn infection." (PMID 30669615, 2019). "Mice deficient in endosomal TLR signalling (TLR3, TLR7 and TLR9) showed heightened susceptibility to infection with a neuroadapted SINV." (PMID 30909385, 2019). "Upon infection, TLR3 recognizes double stranded RNA (dsRNA), leading to signaling pathways that drive the production of Type I interferons (IFNs)." (PMID 31416461, 2019). "Their findings further indicated that in vivo activation of iNKT cells after EV-A71 infection relies on TLR3 signaling in macrophages." (PMID 31787104, 2019). "PolyI:C is recognised by toll-like receptor 3 (TLR3), and a strong inflammatory response is initiated that brings cells to the site of infection in order to help kill the invading pathogen." (PMID 30691477, 2019). "Rhinovirus infection induced more subepithelial PRR+ cells in asthmatic patients, with higher levels of TLR3 and RIG-I expression linked to greater viral load and worse clinical outcomes, suggesting such responses are markers of severity of infection." (PMID 29698627, 2019). "The rate of degradation in TER was significantly higher in the TLR3-deficient OE cells, which resulted in an almost 80% decline in TER by 36hrs post infection." (PMID 30625140, 2019). "A few studies reported the host detrimental effects of LRV during infection and specific mechanisms involving induction of TLR3 activation and type I IFN production." (PMID 31754185, 2019). "Here, we show that Chlamydia has an impact on the stability and function of cellular TJs throughout infection in murine OE cells, and that TLR3 function significantly modulates this effect." (PMID 30625140, 2019). "Muscovy ducks infected with A/Duck/Guangdong/212/2004 (H5N1) upregulated TLR3 expression in their brains, but downregulated it in lungs and spleens, over three days post infection." (PMID 30634569, 2019).
infection (continued). "infection, in which the virus triggers TLR3 signaling to induce autophagy, that inhibits inflammasome activation and enhances parasite’s survival in BMDMs." (PMID 31754185, 2019). "TLR3 knock out mice were less vulnerable to severe West Nile Virus (WNV) infection, cytokine production, neuronal injury and viral replication in brain." (PMID 30735502, 2019). "Our biochemical analyses provided molecular insights into understanding TLR3-mediated detection and downstream signal transduction during EV-A71 infection." (PMID 30563052, 2018). "On the contrary, the percentage of NKG2D on TLR3+ NK cells was significantly decreased after infection (47.43 ± 4.974% versus 12.99 ± 1.155%, P < 0.05)." (PMID 30246036, 2018). "As an important TLR3 downstream transcription factor, NF-κB is best understood in the context of its response to infection and cellular stress." (PMID 29571298, 2018). "Together, these data support a critical role for TLR3 in detecting EV-A71 infection to trigger type I IFN-mediated antiviral immunity." (PMID 30563052, 2018). "The impact of TLRs, especially TLR3 on MHV-68 infection and immune responses remains to be further clarified." (PMID 30075008, 2018). "Their data are interesting and first suggest the role of the TLR3-Trif axis in detecting EV-A71 infection." (PMID 30563052, 2018). "The inflammatory cell infiltrate in the genital tract of wild-type and TLR3-/- mice at middle stages (day 21 of infection) of C. muridarum infection was predominantly composed of lymphocytes when compared with mock-inoculated controls." (PMID 29624589, 2018). "In late-stage infections, both mouse strains developed hydrosalpinx; however, the extent of hydrosalpinx was more severe in TLR3-/- mice." (PMID 29624589, 2018). "The silencing effect of TLR3 on mouse BMMs was confirmed by the decrease in the TLR3 mRNA level even though TLR3, as one of ISGs, was also upregulated upon EV-A71 infection." (PMID 30563052, 2018). "Our current work has shed light on how the TLR3 pathway plays a critical role in detecting EV-A71 infection, thereby triggering type I IFN-mediated antiviral immunity." (PMID 30563052, 2018). "The endogenous TLR3 protein level in SK-N-SH cells was also decreased after EV-A71 infection in a time-dependent manner." (PMID 30563052, 2018). "Because T cells were shown to be important in the control of experimental PCM, we decided to investigate CD4+ and CD8+ T cells in the lung of TLR3−/− and WT mice after 30 days of infection." (PMID 30687643, 2018). "When compared to the healthy, pre-infection stage, the PreAH phase was characterized by significantly greater expression of TLR3 (P < 0.01)." (PMID 30581424, 2018). "Expression of TLR3 in HEK293 cells enabled the cells to sense EV-A71 infection, leading to type I, IFN-mediated antiviral immunity." (PMID 30563052, 2018). "Future work using TLR3 knockout mice is warranted to further confirm the importance of the TLR3-type I IFN axis in protecting from EV-A71 infection in vivo." (PMID 30563052, 2018). "Groups of 5 wild-type and TLR3-/- mice were intravaginally inoculated with C. muridarum, and histological lesions of their uterine horns and oviducts collected at days 7 and 21 of infection were scored as described in Materials and Methods." (PMID 29624589, 2018). "Groups of wild-type and TLR3-/- mice were intravaginally inoculated with C. muridarum, and histological lesions in the lower and upper genital tract at day 56 of infection were scored as described in methods." (PMID 29624589, 2018). "TLR3 recognizes double-stranded RNA (dsRNA) and activates innate immunity against pathogen infection." (PMID 30405139, 2018). "Individual stimulation of TLR3, which senses dsRNA that is expressed upon infection by most RNA viruses including influenza and RSV 6, 19, 20, 21, indeed induced IFN‐β and CXCL10 protein production." (PMID 30184252, 2018).
infection (continued). "In early stage infection, TLR3-/- mice showed a diminished synthesis of IFN-β, IL-1β, and IL-6, but enhanced production of IL-10, TNF-α, and IFN-γ." (PMID 29624589, 2018). "A limitation to the interpretation of the herein rests on the utilization of poly (I:C), a TLR3 agonist, to mimic a viral-like infection." (PMID 30344520, 2018). "Our findings showed that the endometrium and oviducts of TLR3-/- mice exhibited significantly higher lymphocytic inflammation when compared to wild-type mice at day 21 post-infection." (PMID 29624589, 2018). "In conclusion, we report that TLR3-TRAF-NF-κB signaling pathway play a role in the induction of SOCS1 that counteracts the antiviral effect of IFN-γ during MHV-68 infection." (PMID 30075008, 2018). "TLR3-transfected HEK293 cells were used for EV-A71 infection, and the TLR3 protein level was measured using immunoblotting." (PMID 30563052, 2018). "Our results demonstrated that the percentages of MHC II-, CD69-, and NKG2A/C/E-expressing cells in TLR3+ NK cells increased significantly after infection (P < 0.05)." (PMID 30246036, 2018). "Of note, ectopic expression of TLR3 in HEK293 cells resulted in the activation of the IFN-β promoter in response to poly(I:C) stimulation or EV-A71 infection for different times." (PMID 30563052, 2018). "Not only the percentages of MHC II-, CD69-, and NKG2A/C/E-expressing cells but also the percentages of IL-4-, IL-5-, and IL-17-producing cells in TLR3+ NK cells increased significantly after infection (P < 0.05)." (PMID 30246036, 2018). "Results from the siRNA approach showed that TLR3-mediated IFN-β activation upon EV-A71 infection was obviously impaired by the silencing of Trif or TAPE." (PMID 30563052, 2018). "The infection by dengue virus (DENV) of microglia causes cell activation and migration via a mechanism involving viral entry, RNA release, and Toll-like receptor 3 signaling." (PMID 30563082, 2018). "The percentage of MHC II-expressing NK cells from TLR3 KO mice was less than WT after infection in statistics (P < 0.05)." (PMID 30246036, 2018). "ATMUV is highly pathogenic to avians especially to ducks; during ATMUV infection of DEF cell and 293T cell, the expression of both duck TLR3 and huTLR3, respectively, and other inflammatory cytokines like IL-2, IL-6, and IL-29 are raised." (PMID 29888293, 2018). "TLR3-deficient DCs produced strikingly less TNF-α and IL-10 and exhibited a slight increase in IL-23 secretion 12 hours after infection." (PMID 28973047, 2017). "Since EVs released during infection can contain pathogenic RNA38, 39, the involvement of endosomal TLRs in macrophage activation was assessed by stimulating mBMDM from TLR3/7/9 knockout animals." (PMID 28740179, 2017). "Following recognition by TLR-3, infection of fetal brain cells with ZIKV impairs the neurosphere and brain organoid growth." (PMID 28676848, 2017). "For example, infection with West Nile virus, an ssRNA virus, initiates an inflammatory response through TLR3, as Tlr3−/− mice are more resistant to infection with the virus." (PMID 28878771, 2017). "With the purpose of verifying the role of TLR3 in resistance to infection, we infected WT and TLR3 KO mice with CVB3 and monitored their survival." (PMID 28973047, 2017). "As TT was identified as a high-TBE-risk genotype, this result agrees well with TNFα expression promoting the disease onset and provides a link between the TLR3 expression and the TNFα synthesis during an infection with TBEV in vivo." (PMID 28646884, 2017). "Upon infection with WNV, several PRRs including MDA5 (melanoma differentiation-associated protein 5), TLR3, TLR7, and RIG-I (retinoic acid-inducible gene 1) determine the molecular patterns of WNV." (PMID 28676848, 2017). "It has been shown that ZIKV (MR766) infection increases the expression of Toll-like receptor 3 (TLR3), another innate immune receptor that recognizes dsRNA, in iPS-derived human cerebral organoids and neurospheres." (PMID 28878742, 2017).
infection (continued). "Further, our investigation with KRAS mutated HCT116 cell line showed that effective expression of host TLR3 dampens the infection potential of reovirus by mounting a robust innate immune response." (PMID 28422714, 2017). "TLR1, TLR3, TLR7, and TLR8 are strongly repressed, with the appearance of the eggs at week 8 after infection, and TLR3 shows most repression." (PMID 29225962, 2017). "In accordance with S. suis-induced IFN-β production by DCs being mostly MyD88-dependent, the TLR3, which is MyD88-independent and recruits TRIF, was only minimally implicated, and only following infection with the SLY-negative ST25 strain 89-1591 (p < 0.05)." (PMID 28894449, 2017). "Treatment with the TLR3 agonist poly(I:C) decreased the size of neurospheres in a similar fashion to the infection with ZIKV." (PMID 28878742, 2017). "This strongly mirrors the mammalian response to infection where Toll-like receptors such as TLR3 are upregulated in response to infection." (PMID 28713778, 2017). "The observation that TLR3 is upregulated following infection suggests that TLR3 plays a role in the innate recognition of RABV." (PMID 29403485, 2017). "In vivo experiments in chickens further confirmed the observed inflammatory and innate responses induced by vvIBDV in DT40 cells in vitro, and IL-1β, IL-18, TLR1, TLR2, and TLR3 are the predominant DE genes after vvIBDV infection." (PMID 28086922, 2017). "We found that the expression of TLR-3 induced by PR8 (at 24 h post-infection) was markedly impaired by treatment with R. isatidis polysaccharides at higher doses (30 mg/mL or 15 mg/mL) but not at a lower dose (7.5 mg/mL), indicating dose-dependent inhibition." (PMID 28085062, 2017). "The TLR3 expression was down-regulated in the early stage of infection (1 and 6 hpi) and up-regulated at 24 hpi (1.58- and 1.88-fold, respectively) in both Z8S2 and Z8R2 groups when compared with group Z7." (PMID 28674528, 2017). "Among the genes associated with responses to virus, TLR3, IRF1, GATA3, SAMHD1 and RSAD2 were all significantly up-regulated on both day 1 and day 3 post infection." (PMID 28486945, 2017). "Strikingly, transfection of TLR3-siRNA and MDA5 shRNA significantly disrupted the expression of both TLR3 and MDA5, associated with lower mRNA levels of IFN-β, IL-28A/B, IL-29 after ATMUV infection than those observed in cells silencing MDA5 only." (PMID 27449021, 2016). "A previous study reported that TLR3-primed infection up-regulated the expression of IRF3 in mouse MSCs42." (PMID 27444640, 2016). "We also examined the expression levels of TLR3 before and after the infection in RD and HT-29 cells." (PMID 27007979, 2016). "The mRNA expression level of TLR3 in P815 cells infected with IAVs peaked 4 h post-infections, and returned to baseline levels by 12 h post-infection." (PMID 28127293, 2016). "The expression of these pro-inflammatory cytokines and chemokines was significantly decreased in TLR3/dsRNA complex inhibitor treatment group 24 and 36 h after infection." (PMID 28127293, 2016). "Significant increases in IFNA, IFNG and TLR3 mRNA expression are reported during HPAI infection of chicken dendritic cells." (PMID 27071061, 2016). "All data point to the importance of TLR3 SNPs in the development of infections and infection-induced diseases." (PMID 27227908, 2016). "IL-17-/- mice also showed a reduced parasite burden at the peak of infection, thus inferring a detrimental role for LRV1-dependent IL-17A and confirming the existence of a pathogenic TLR3-IL-17A signalling axis." (PMID 27658195, 2016). "Infection in bone marrow chimeric mice provided evidence on how TLR3-expressing hematopoietic cells are required to elicit an anti-CHIKV innate immune response and regulate CHIKV infection and pathology." (PMID 25452586, 2015). "In the in vitro HD11 cell infection model, mRNA expression levels of TLR3, which recognises dsRNA (IBDV is a dsRNA virus), were also upregulated." (PMID 25884204, 2015).